MYC (MYC proto-oncogene, bHLH transcription factor)
Diseases named in the same sentence as MYC in open-access papers (continued):
Sharing a sentence is not in itself a finding about the gene and the disease.
lymphoma (continued). "When animals were immunized with c-MYC protein prior to lymphoma challenge, tumors grew out at the site of injection at the same pace as in OVA-immunized control animals." (PMID 24130880, 2013). "The nuclear factor CYCLON is a new MYC cooperating factor that drives tumor growth and Rituximab resistance in lymphoma." (PMID 23828858, 2013). "High CYCLON expression was observed in BL, an MYC-dependent lymphoma, and in aggressive DLBCL (of both the GCB and ABC subtypes), but not in other lymphoid malignancies." (PMID 23828858, 2013). "In summary, this work has identified CYCLON as a new MYC cooperating factor that autonomously drives aggressive tumour growth and Rituximab resistance in lymphoma." (PMID 23828858, 2013). "We first performed a dose-response experiment to test the effects of JQ1 on MYC levels in our panel of lymphoma cell lines." (PMID 23828858, 2013). "CYCLON knockdown was found to inhibit the aggressivity of MYC-overexpressing tumours in mice and to modulate gene expression programs of biological relevance to lymphoma." (PMID 23828858, 2013). "We will use the model to study the major cellular processes involved in MYC-induced lymphoma, osteosarcoma, and hepatocellular carcinoma, which involve difference combinations and sequences of these programs and to test different therapeutic strategies." (PMID 23573174, 2013). "We use this to model oncogene addiction in MYC-induced lymphoma, osteosarcoma, and hepatocellular carcinoma." (PMID 23573174, 2013). "Extending this Eμ-Myc-lymphoma model to human B cell lymphomagenesis, the relationship between MYC and BIM in EBV-negative BL was investigated." (PMID 24167519, 2013). "Coincident CYCLON and MYC deregulation was detected in 5 of 8 lymphoma cell lines tested (BL cell lines Raji, BL41 and BL136 and in the GCB-type DLBCL, B593 and SUDHL4)." (PMID 23828858, 2013). "Small molecule inhibitors of BET bromodomain proteins (JQ1, iBET) have recently been shown to attenuate MYC-driven oncogenic signalling in lymphoma and myeloma." (PMID 23828858, 2013). "Using this model, we demonstrate for the first time that picolog administered in vivo is well tolerated and can inhibit the growth of aggressive, MYC-induced lymphoma." (PMID 22308267, 2012). "The mouse lymphomas are phenotypically similar to normal immature or transitional B cells and together with tumors of λ-MYC TG mice have been classified as diffuse high-grade blastic B cell lymphoma/leukemia (DBLL)." (PMID 22754359, 2012). "The characteristic rearrangements of a DH lymphoma are the two chromosomal translocations involving MYC, BCL2 och IGH." (PMID 23171647, 2012). "In contrast, the λ-hu-MYC lymphoma is a poorly immunogenic, highly malignant tumor that rapidly progresses in wild-type mice in the absence of OVA and/or GFP (progressor phenotype)." (PMID 22479645, 2012). "We have shown that the simplified bryostatin analog, picolog, which can be synthesized in quantities needed for clinical advancement, has superior in vitro activity to bryostatin 1 in inhibiting growth and inducing apoptosis in MYC-induced lymphoma." (PMID 22308267, 2012). "We utilized two types of lymphomas, λ-hu-MYC lymphomas into which OVA-IRES-GFP had been introduced by retroviral transduction as well as lymphomas arising spontaneously in β-Act-OVA/λ-hu-MYC double transgenice mice." (PMID 22479645, 2012). "A DBLL cell line derived from a λ-MYC lymphoma that was treated with an ARF-BP1-specific siRNA had greatly increased levels of each of these proteins, consistent with studies performed with cells from other lineages." (PMID 22754359, 2012). "In vitro, picolog is remarkably potent for inhibition of growth of MYC-induced lymphoma and leukemia cells, with activity seen at concentrations as low as 50 nM in vitro." (PMID 22308267, 2012). "But this specific group comprises of >30% of MYC-translocation-positive lymphomas in elderly patients and has an aggressive clinical course." (PMID 22548066, 2012).
lymphoma (continued). "Using a conditional c-MYC expressing lymphoma cell line, we showed that miR-27a and miR-24 were coordinately regulated, along with miR-23a, by c-MYC." (PMID 23236401, 2012). "The similarities between a chemical carcinogen-induced murine sarcoma and our λ-hu-MYC lymphoma model into which OVA and GFP were introduced as foreign antigens are intriguing." (PMID 22479645, 2012). "Recent studies showed that SKP2 is expressed at high levels in most BL as well as lymphomas of Eμ-MYC transgenic (TG) mice." (PMID 22754359, 2012). "We analyzed CD3-epsilon−/− mice for tumor growth following transplantation of 105 GFP+ TBL (Triple-Transgenic B cell Lymphoma) lymphoma cells, which are derived from an E-mu-MYC/BCRHEL/sHEL transgenic mouse." (PMID 22880059, 2012). "To study mechanisms of T cell-mediated rejection of B cell lymphomas, we developed a murine lymphoma model wherein three potential rejection antigens, human c-MYC, chicken ovalbumin (OVA), and GFP are expressed." (PMID 22479645, 2012). "These E-mu-MYC/BCRHEL/sHEL lymphomas (TBLs – Triple Transgenic B cell Lymphoma) most closely resemble human BL." (PMID 22880059, 2012). "Recently, a cell line was established from a patient with this complex lymphoma and analyzed using conventional tools revealing it contains both MYC and BCL2 translocation events." (PMID 23171647, 2012). "Picolog, compared to bryostatin, exhibited superior growth inhibition of MYC-induced lymphoma in vitro." (PMID 22308267, 2012). "As a plausible proof of concept for the function of c-Myc in lymphoma stem cells, Eμ-MYC lymphoma cells were almost homogenously able to initiate lymphomas in transplantation experiments." (PMID 24212774, 2011). "Especially our discovery of MYC as a transcription factor involved in B-cell differentiation and B-cell signaling is of great importance for a better understanding of MYC-driven lymphomas such as BL." (PMID 22102868, 2011). "Recently, the LIN28 family member LIN28B, whose expression in highly elevated in a number of human tumors, was shown to be a direct MYC target in P493-6 B cells and mouse lymphoma." (PMID 22039435, 2011). "A similar type of senescence has been reported for lymphoma, osteosarcoma, and hepatocellular carcinoma tumors upon c-MYC inactivation." (PMID 20585577, 2010). "In certain lymphomas, Myc over-expression results from a chromosomal translocation of MYC into an immunoglobulin gene locus, which suffices to drive the high-level expression of the proto-oncogene in the pre-B or B cell environment." (PMID 21060841, 2010). "On the other hand, MYC has been shown to induce angiogenesis in conjunction with HIF1 alpha by means of VEGF in lymphomas and epidermal lesions." (PMID 19551151, 2009). "In contrast to what we observed in the lung, we found that MYC (LM) was a much more potent oncogene than K-rasG12D (LR) at inducing lymphomas with a median latency of tumor onset of 13 weeks versus more than 100 weeks (p<0.0001 by log rank)." (PMID 18461184, 2008). "In contrast, Stat3 becomes dephosphorylated in lymphoma cells upon inactivation of MYC and/or K-rasG12D." (PMID 18461184, 2008). "We obtained serial tail vein blood samples from mice with MYC-induced lymphoma before and after oncogene inactivation." (PMID 18826639, 2008). "MYC-, K-rasG12D- or MYC/K-rasG12D-induced lymphomas exhibited sustained regression upon the inactivation of either or both oncogenes." (PMID 18461184, 2008). "The Eμ-MYC/BCRHEL mice developed fatal lymphomas more rapidly than did Eμ-MYC mice, and the anatomical distribution of the tumor was different." (PMID 18578569, 2008). "Our results indicate that both the unstimulated and stimulated states of the receptor can cooperate with an oncogene known as MYC in the genesis of lymphomas." (PMID 18578569, 2008). "MYC-, K-rasG12D- or MYC/K-rasG12D-induced lymphomas exhibited sustained regression upon single or double oncogene inactivation." (PMID 18461184, 2008).
lymphoma (continued). "Collectively our results illustrate that for both MYC/K-rasG12D-induced lung tumors and lymphomas dephosphorylation of Stat 3 is correlated with the ability of oncogene inactivation to induce tumor regression." (PMID 18461184, 2008). "LM, LR, and LMR lymphoma cells all exhibited phosphorylation of Stat3 that decreased upon inactivation of MYC and/or K-rasG12D." (PMID 18461184, 2008). "To study how MYC and K-rasG12D cooperate for the initiation and maintenance of tumorigenesis, we have generated double conditional transgenic mouse models of lymphoma and lung adenocarcinoma." (PMID 18461184, 2008). "Previous work has shown that overexpression of MYC in the B cell lineage can give rise to lymphomas in mice." (PMID 18578569, 2008). "In the present work, an autogenous signal from a mature BCR cooperated with MYC to produce a lymphoma that was distinctively different from the tumor produced when the same BCR was subjected to sustained antigenic stimulus." (PMID 18578569, 2008). "For lymphomas, inactivation of MYC or K-rasG12D alone or both MYC/K-rasG12D induced reversible tumorigenesis." (PMID 18461184, 2008). "It has been shown in two independent studies that bruceantin is able to down-regulate c-MYC protein expression in a panel of leukemia, lymphoma, and myeloma cell lines." (PMID 17254356, 2007). "Despite the fact that they do not overexpress c-MYC protein, MMTV-RARαG303E lymphomas resembled, histologically and phenotypically, other types of high grade lymphomas with transitional phenotype, such as the ones driven by deregulated MYC expression." (PMID 16563162, 2006). "We show that MCL-1i and CD19-targeted CAR-T cells reciprocally overcome resistance to each single-agent therapy, and combining MCL-1i with CD19 CAR-T cells significantly improves treatment efficacy, resulting in near-complete eradication of MYC-driven lymphoma in vivo." (PMID 41680300, 2026). "We hypothesized that the combination of enitociclib, venetoclax and prednisone (VVIP) would be active in R/R aggressive lymphomas, many of which express increased MYC, BCL2 and MCL1." (PMID 41169010, 2026). "c-MYC repression across six lymphoma cell lines correlated with BCL6 levels." (PMID 40166243, 2025). "Interestingly, aberrant expression of MYC was found in EBV-infected lymphoma cells, both in BL and other lymphomas." (PMID 40349096, 2025). "In the case with composite EMZL and EBV‐positive DLBCL (case 6), both lymphomas harboured 23 common variants, including mutations in CD274, TET2, and TNFRSF14, and the EBV‐positive DLBCL showed an additional MYC translocation and a further 20 variants over the EMZL component." (PMID 39722652, 2025). "The earlier induction of LMP1 under hypoxia may be linked to the observed reduction in MYC expression, as previous findings indicate that c-MYC represses LMP1 transcription in EBV-infected lymphoma cells and LCL models." (PMID 40313738, 2025). "PEAR-ChIP has also discovered previously unknown repetitive enhancer events at the MYC location and enhancers unique to certain subtypes in lymphoma." (PMID 39838405, 2025). "In cases of DLBCL, immunohistochemical staining for BCL2 and c-MYC identifies “double expresser” lymphomas, a subgroup associated with a poor prognosis, though not as severe as double-hit lymphomas." (PMID 40428800, 2025). "Furthermore, when the MYC rearrangement partner is represented by the immunoglobulin genes (IG), double hit lymphomas (MYC/BCL2-DH) are characterized by a worse clinical outcome, but the reason for this is unclear." (PMID 41008653, 2025).
lymphoma (continued). "Employing a pharmacological screen, we demonstrate how targeting PRPS1 or PRPS2 elicits opposing sensitivity or resistance, respectively, to chemotherapeutic agents affecting the thioredoxin and glutathione network, thus providing a therapeutic blueprint for treating MYC-driven lymphomas." (PMID 39868212, 2025). "In contrast, lymphomas with dual MYC and BCL6 rearrangements represent a more diverse group and have variable gene expression profiles and mutational spectra, making them markedly different from DLBCL/HGBL-MYC/BCL2." (PMID 40126346, 2025). "In conclusion, an analysis of 93 cases, including our four cases, suggests that MYC rearrangement contributes to immature immunophenotypic profiles in both lymphoma and leukemia, emphasizing the importance of a refined classification that integrates morphology, immunophenotype, and genetics." (PMID 41142614, 2025). "Furthermore, 13 patients (18.8%) had their diagnosis changed from high-grade lymphoma to BL following detection of IGH/MYC translocations." (PMID 40703543, 2025). "c-MYC is a critical oncogenic driver expressed in all germinal center-derived lymphomas that regulates cell proliferation required for formation and maintenance of germinal centers, prompting us to examine the contribution of its loss to the antiproliferative mechanism." (PMID 40166243, 2025). "Similarly, the double-expressor phenotype was also less prevalent in PT-DLBCL, while BCL6 rearrangements, double-expressor phenotype, and even double-hit lymphomas involving MYC and BCL6 or BCL2 are reported more frequently in western countries." (PMID 41244893, 2025). "Notably, Myc facilitates the MYC–AURKA/PLK1 axis feed-forward circuit in lymphomas and neuroblastomas." (PMID 40813622, 2025). "Loss of DDX3X function prevents MYC oncogene-driven lymphomagenesis by moderating global protein synthesis and buffering MYC-induced proteotoxic stress, but established male lymphoma cells can overcome this effect by aberrantly upregulating DDX3Y protein levels." (PMID 39975375, 2025). "While antioxidants may slow tumor progression in specific cancers such as MYC-driven lymphoma, they can accelerate tumor growth, metastasis, and angiogenesis in other settings, including KRAS-driven lung cancer and BRAF-driven melanoma." (PMID 40646353, 2025). "This belief vanquished in 1982 when my lab and subsequently the Leder lab showed the juxtaposition of the human MYC oncogene, the homolog of the avian MYC gene responsible of lymphoma in chicken, to the human immunoglobulin heavy chain locus in Burkitt lymphoma cells." (PMID 40204952, 2025). "In addition, while the MYC rearrangement in BL commonly occurs in the background of a simple karyotype, MYC rearrangements in other lymphomas often have additional chromosomal rearrangements and abnormalities." (PMID 41154426, 2025). "A key gene associated with dysregulated carbohydrate and lipid metabolism in lymphomas is MYC." (PMID 40349096, 2025). "DCR-MYC, a synthetic siRNA targeting MYC encapsulated in EnCore lipid nanoparticles, was evaluated in patients with advanced solid tumors, multiple myeloma, and lymphoma, demonstrating a favorable safety profile (NCT02110563)." (PMID 40390104, 2025). "Importantly, pharmacological GCL inhibition hindered lymphoma growth in female λ-MYC mice, suggesting that this treatment holds promise as a therapeutic strategy for female lymphoma/leukemia patients." (PMID 39068166, 2024). "Furthermore, findings from another study indicated that high CD38 protein expression is a significant indicator of MYC rearrangement in high‐grade B‐cell lymphomas, a category that includes aggressive lymphomas such as BL." (PMID 39364393, 2024). "In this study, targeted deep sequencing of 128 highly lymphoma-relevant genes was applied to identify pathogenic variants and CNVs in 26 patients with DLBCL-NOS involving the ocular adnexa and 2 patients with HGBCL with MYC and BCL2 rearrangements." (PMID 38542066, 2024).
lymphoma (continued). "MCL may also gain secondary BCL2, BCL6, and MYC rearrangements, as proposed in three of the previously reported quadruple hit lymphomas." (PMID 38914869, 2024). "Furthermore, treating MYC-dependent mouse lymphoma and hepatoblastoma with CDK1 inhibitors has been shown to reduce tumor growth and prolong survival time." (PMID 38638876, 2024). "In other studies, its up-regulation was observed in MYC-induced lymphomas; however, it was not implicated in the promotion of lymphoma." (PMID 39263534, 2024). "In addition, reducing the expression of single RP genes, like RPL24 or RPL38, in Eμ-MYC mice led to a 20% decrease in lymphoma incidence and delayed tumor onset, highlighting the significance of accurate translational control." (PMID 39596100, 2024). "“Double hit” lymphomas with MYC and BCL2/BCL6 alterations confer a poor prognosis." (PMID 38534887, 2024). "Approximately 40% of cases are DPE lymphomas, being positive for both MYC and BCL2 proteins." (PMID 39684922, 2024). "This was confirmed in a multicentre retrospective data collection study, which showed that MYC + BCL6 DH lymphoma does not represent high-risk lymphoma, while MYC + BCL2 DH lymphoma has particularly poor prognosis." (PMID 38965209, 2024). "In both cases, the MYC protein expression was weak in <40% lymphoma cells." (PMID 38184753, 2024). "In addition, there is the term “dual or double expressor” lymphoma (DEL) that refers to MYC/BCL2 or MYC/BCL6 protein co-expression and triple expressor lymphoma (TEL) that refers to MYC/BCL2/BCL6 protein co-expression by IHC." (PMID 39038016, 2024). "Having found that loss of Arrdc3 confers a competitive advantage in malignant Eμ-Myc lymphoma cells, and having generated an Arrdc3 knockout mouse model, we next investigated whether Arrdc3 might impact MYC-driven lymphoma development in vivo." (PMID 38097622, 2024). "The aggressive behavior of this lymphoma may be due to the aberrant expression of BCL2, causing increased apoptotic resistance, and MYC activation, causing proliferation." (PMID 39684922, 2024). "We next evaluated whether lymphoma-intrinsic MYC could suppress the activity of effector T-cells by comparing their cytokine release after T-cell engager blinatumomab-mediated cytotoxicity against parental OCI-LY18 WT versus MYC downregulated cells." (PMID 39596160, 2024). "Furthermore, the inter-dependent regulatory relationship between MondoA, TXNIP, and MYC has been seen in a variety of models, whilst the impact of NAC on MYC-dependent pathways has been seen in lymphoma." (PMID 39103698, 2024). "HGBCL lymphomas carry abnormal MYC and BCL2 via different mechanisms." (PMID 38918775, 2024). "In many of these lymphomas (up to 80% in some case series), the rearrangement of MYC together with that of BCL2 and/or BCL6 has been identified, a condition defined as “double-hit” (DH) or “triple-hit” (TH) lymphomas depending on the number of pathogenetically relevant lesions identified." (PMID 38534887, 2024). "Conspicuously, and perhaps surprisingly, (almost entirely) absent as a major variable in the stratification of the different genomic categories of DLBCL is testing for a MYC translocation that has long been a key component of evaluation of this group of lymphomas." (PMID 37747559, 2024). "Moreover, the inhibition of SUMOylation persuades the apoptosis of MYC-dependent lymphoma cells and signifies it as an attractive therapeutic option." (PMID 38590645, 2024). "First, it may explain why MYC overexpressing lymphomas are often refractory to R-CHOP immunochemotherapy." (PMID 39596160, 2024). "This lymphoma represents a morphologically, genetically, and clinically heterogeneous entity and the detection of MYC-R associates with a poorer outcome after standard chemoimmunotherapy, as HGBL carrying MYC and BCL2 rearrangements." (PMID 37368083, 2024).